LGR5 (leucine rich repeat containing G protein-coupled receptor 5)
Diseases named in the same sentence as LGR5 in open-access papers (continued):
Sharing a sentence is not in itself a finding about the gene and the disease.
tumor (continued). "In contrast, the mRNA expression of both Lgr5 and Sox9 was significantly downregulated in these tumours when compared with normal skin." (PMID 32397255, 2020). "LGR5 elimination transiently retarded local tumor growth, possibly reflecting CIC plasticity, where differentiated cells can revert to LGR5+ CIC." (PMID 31921628, 2019). "Our simultaneous assessment of these two molecules in GC patients, by IHC, demonstrated that the up-regulation of LGR5 coincides with the down-regulation of TROY in the tumor tissue." (PMID 30501144, 2019). "The positive rates of CD133, CD44v6, ALDH1 and LGR5 expression in the primary tumour samples were 59.2% (173/292), 72.9% (213/292), 45.9% (134/292) and 81.8% (239/292), respectively." (PMID 31000786, 2019). "Several other studies have reported that Lgr5 is highly expressed in tumor tissues with nuclear accumulation of β-catenin, which is crucial for the activation of the Wnt signaling pathway." (PMID 31417548, 2019). "Further assays via lineage tracing of the differentiated tumor cells demonstrated that these cells restored the LGR5+ CSC pool." (PMID 31317205, 2019). "Nevertheless, little is known about the specific interactions between Lgr5 and the immunosuppressive tumor microenvironment in gastrointestinal tumors." (PMID 31417548, 2019). "Based on our data, a shift toward the production of Th2 cytokines occurs in the tumor microenvironment of GC patients with high expression of Lgr5." (PMID 31417548, 2019). "TROY expression in the tumor tissue was significantly lower than that of the adjacent tissue (2.5 ± 0.9 vs. 3.3 ± 0.9, p = 0.004), which was coincident with higher LGR5 expression (3.6 ± 1.1 vs. 2.7 ± 0.9, p = 0.001)." (PMID 30501144, 2019). "Here, therapeutic ablation of the tumor-specific Lgr5+ cells in xenografts initially leads to impaired tumor growth." (PMID 30927915, 2019). "In human CRC, LGR5+ cells have self-renewal and differentiation capacity and fuel tumour growth as cancer stem cells." (PMID 31097693, 2019). "Mice with specific deletion of PKM2 in Lgr5+ or Villin+ cells exhibited enhanced tumor progression in the AOM/DSS-induced CRC murine model." (PMID 30996297, 2019). "Ablation of Lgr5+ cells in orthotopically transplanted tumors, generated by genetic modification in differentiated villus cells, suppressed tumor growth." (PMID 31905853, 2019). "LGR5+ CRC cells were shown to be tumour initiating cells in murine CRC and required for the development and maintenance of liver metastasis." (PMID 31097693, 2019). "In the primary tumor, LGR5 was found in the tumor center in 72 (71.3%; valid n = 101) and at the invasion front in 71 (70.3%) primary GCs." (PMID 31827644, 2019). "Discrepant results of reports on the effects of Lgr5 expression in tumor progression have been presented in the literature." (PMID 31358061, 2019). "In colorectal differentiated tumor cells, NF-κB signaling has been shown to activate the Wnt pathway to induce dedifferentiation, re-expression of Lgr5, gain of stem cell properties, and increased tumor initiation ability." (PMID 31557977, 2019). "Recent work has provided insight into limitations on the efficacy of directly targeting LGR5+ CRC stem cells in primary tumours." (PMID 30792270, 2019). "Further statistical analysis based on IHC suggested a significant positive correlation between FoxP3+ Tregs number and Lgr5 expression in tumor tissues (P < 0.0001; 9.77 ± 5.23 vs. 5.20 ± 4.50)." (PMID 31417548, 2019). "Taken together, Lgr5 emerges as a potential surface-expressing biomarker for targeted anti-tumor therapy." (PMID 31358061, 2019). "Unexpectedly, while in normal crypts the Notch1 and Lgr5 transcripts are enriched within the same cells, Notch1+ tumour cells showed a reduction in Lgr5 expression compared to non-labelled cells." (PMID 30696875, 2019). "LGR5 expression in tumor cells of primary GCs correlated only with lymph vessel invasion (L category, p = 0.002)." (PMID 31827644, 2019).
tumor (continued). "LGR5 positive cells in the tumor has been reported to have increased TCF/LEF activity along with increased clonogenic potential both in vitro and in vivo." (PMID 31608135, 2019). "Numerous studies have reported the stimulatory effects of Lgr5 in tumor growth through the regulation of CSC stemness, epithelial-mesenchymal transition (EMT), and cancer cell proliferation." (PMID 31358061, 2019). "The relationship between the number of intratumor FoxP3+ Tregs and Lgr5 expression in tumor tissues was analyzed by IHC and IF." (PMID 31417548, 2019). "Tamoxifen-inducible Lgr5-driven deletion of PKM2 in ISC (PKM2ΔLgr5-Tx) significantly promoted tumor incidence and size in the colon and lower body weight compared with findings in vehicle-treated mice (PKM2ΔLgr5-Veh)." (PMID 30996297, 2019). "While the expression of MIST and FZD7 at the tumor surface, tumor center, and invasion front was interrelated significantly, no such interrelation between different tumor compartments was found for LGR5." (PMID 31827644, 2019). "The analysis confirmed a (moderate) increase in the expression of Ascl2 and other Wnt target genes Axin2, Lgr5, and SP5 in Apc/Msx−double-deficient tumor cells when compared to the cells with intact Msx1 gene." (PMID 30733598, 2019). "Lgr5 is crucial for tumor initiation, progression, and metastasis through regulation of CSC function, Wnt/β-catenin signaling pathway, and various other signaling pathways." (PMID 31358061, 2019). "In the neoplastic epithelium of the OSCCs the LGR5 expression was diffusely expressed throughout the tumor mass except the keratinized central areas." (PMID 30770730, 2019). "After in vivo Apc depletion in leucine-rich-repeat containing G-protein-coupled receptor 5 (Lgr5)+ crypt stem cells, tumor formation occurred within 3–5 weeks." (PMID 31905853, 2019). "Of relevance, our results define a cellular hierarchy within tumours, whereby Notch1+ CSCs appear to be giving rise to Lgr5+ tumour cells." (PMID 30696875, 2019). "A recent study reported that RSPO1 (a Lgr5 natural ligand)-conjugated liposomes encapsulating doxorubicin led to massive tumor tissue necrosis and growth inhibition through efficient targeting of Lgr5+ CSCs in a patient-derived xenograft tumor model." (PMID 31358061, 2019). "In this study, we aimed to examine the interactions between Lgr5 and the Treg-mediated tumor immunosuppressive microenvironment in human GC, as well as mechanisms by which Tregs promote Lgr5 overexpression in GC." (PMID 31417548, 2019). "Both LGR5 knockdown and Wnt-C59 reduced tumor invasion and migration and blocked EMT by inhibiting the Wnt/β-catenin pathway in vitro and suppressed the intracranial orthotopic xenograft growth and prolonged the survival of xenograft mice in vivo." (PMID 30208924, 2018). "LGR5 acts as a stem cell marker and controls tumor progression through its downstream Wnt/β-catenin-signaling pathway." (PMID 30089773, 2018). "Studies examining the function of LGR5 in CRC cells have produced confusing and contradictory results, with some studies suggestive of a pro-tumourigenic role for LGR5 while others indicate a tumour-suppressive role." (PMID 29149105, 2018). "Tumor budding (TB) was found in 145 (71.1%, 145/204) tumors, of which 81% (118/145) showed Lgr5 expression." (PMID 30046385, 2018). "We found that tumor size ≥ 2 cm, LN metastasis, and TNBC were associated with high levels of LGR5 expression (p = 0.002, p = 0.044 and p = 0.029, respectively)." (PMID 29471794, 2018). "Taken together, our results demonstrate that Lgr5 expression in CRC is higher at invasion fronts than at the tumor center in a heterogeneous fashion." (PMID 30046385, 2018). "Compared to the tumor epicenter (n = 16.7%, 34/204), Lgr5 expression was significantly higher at the infiltrating (n = 59.5%, 110/185) and expanding fronts (n = 36.4%, 59/162) (P < 0.01)." (PMID 30046385, 2018).
tumor (continued). "Given recent findings that a degree of normal clonal architecture is retained in CRCs,21,67 it is unsurprising that LGR5 plasticity has also been observed in tumours." (PMID 29844449, 2018). "Knockdown of LGR5 cells reduced proliferation and tumor sphere formation in vitro, and impaired tumor formation in vivo." (PMID 29428975, 2018). "Tumor budding (TB) was discovered with significantly higher Lgr5 expression (n = 39.3%, 57/145, P = 0.03) and significantly positively correlated between Lgr5 expression and TB grade (r = 0.19, P = 0.02)." (PMID 30046385, 2018). "The authors showed that although the selective elimination of LGR5+ initially reduced tumor growth, the LGR5+ population subsequently reappeared, as demonstrated by the regrowth of the tumor." (PMID 29491834, 2018). "Src activation in ISCs is sufficient to drive intestinal hyperplasia, while conditional knock out of Apc and Src within Lgr5+ve stem cells resulted in reduced tumour burden and increased animal survival." (PMID 29498662, 2018). "This implies the contribution of additional factors to EGFRi sensitivity and this study suggests tumours with low LGR5 expression will exhibit increased sensitivity." (PMID 29149105, 2018). "Immunofluorescence (IF) analysis of endogenous LGR5 protein confirmed that this particular stem cell-like tumor population was reduced in the Jag1 KO mice (from 48 in the WT to 21% in average), whereas the ISC compartment of normal crypts remained unaffected." (PMID 30065304, 2018). "High Lgr5 expression in tumor buds was also significantly correlated to high tumor budding, positively correlated to the depth of invasion, lymph node metastasis, pTNM stage, and perineural invasion." (PMID 30046385, 2018). "Although there are various CSC marker genes, several recent studies showed that LGR5 has significant effects on tumor growth and metastasis, especially in colorectal cancer." (PMID 29700375, 2018). "LGR5 is regarded as a marker for tumor stem cells and has been shown to be up-regulated in highly tumorigenic primary NB cells, which are able to form tumor spheres in nude mice." (PMID 29058015, 2018). "Patient-derived intestinal stem cell-derived tumor organoids marked by LGR5 recapitulated several properties of the original tumor architecture, cell composition, and self-renewing capabilities." (PMID 29561796, 2018). "We compared stemness traits of colon CSCs by cell surface marker (CD133 and Lgr5) and functional assays, such as chemoresistance, colony formation, cell adhesion, invasion and tumour-formation assay." (PMID 30220706, 2018). "Studies of LGR5 expression in primary tumour samples and of LGR5 function (including the impact on Wnt signalling) have also suggested a potential tumour suppressive function in CRC development." (PMID 29844449, 2018). "This review will recap the various oncogenic and tumour suppressive roles that have been described for the LGR5 molecule in CRC." (PMID 29844449, 2018). "Macrophages serve an important function in the endometrium to maintain fertility, while LGR5+ cells generally have a role in tumor progression and are involved in invasion in some cancers." (PMID 30577586, 2018). "In this work, we have determined the biologic basis of CtBP2’s neoplastic activities in Apc-mutated neoplasia as linked to its regulation of TIC populations and transcriptional regulation of downstream Wnt targets, such as LGR5, c-Myc and cyclin D1." (PMID 30197752, 2018). "Collectively, these studies suggest that, similar to normal gut homeostasis, there are stages of tumour growth where the LGR5 molecule is functionally redundant." (PMID 29844449, 2018). "This review will discuss the various oncogenic and tumour suppressor roles previously ascribed to LGR5 in CRC." (PMID 29844449, 2018). "The LGR5− fraction was not functionally equivalent to LGR5+ CSCs because of their inferior capacity to drive tumour growth, and LGR5 positivity was ultimately necessary for metastatic progression of CRC." (PMID 29844449, 2018).
tumor (continued). "Intriguingly, the different tumours induced by stabilizing β-catenin in Lgr5+, Lgr6+, and Lrig1+ epithelial cells exhibit both similarities and differences in stromal composition." (PMID 29807713, 2018). "In fact, the targeted deletion of JAGGED1 in LGR5+ tumor-initiating cells resulted in the silencing of HES1 expression, the disruption of the stem cell niche and a dramatic reduction in the proliferative activity of APC-deficient intestinal tumors in vivo." (PMID 29652830, 2018). "The expression level of Ki67, a sign of proliferation for tumor malignancy, was higher in LGR5+ xenografts than that in LGR5− xenografts (P < 0.05, n = 5)." (PMID 30208924, 2018). "The concordance rate of Lgr5 expression and the evaluation of tumor budding was 93.6% and 92.2% respectively between two experienced pathologists." (PMID 30046385, 2018). "It is possible that EpCAM-, E-cadherin- and LGR5-carrying EVs participate to the preparation of the microenvironment to accommodate the subpopulation of tumor stem like cells originating from the LCC." (PMID 29137313, 2017). "The expression level of LGR5 in liver tumor tissues and adjacent non-tumor tissues were detected adopting immunohistochemistry (IHC), real-time PCR (RT-PCR) and western blot assays." (PMID 28881613, 2017). "The mRNA levels of c-myc, Birc5, Cd44, Lgr5, Tcf7, Mmp7, and Ephb3 were significantly increased in tumor area compared with non-tumor area." (PMID 28710436, 2017). "The positive rate of LGR5 protein was significantly higher in HCC tissues than in adjacent non-tumor ones (88.5% vs. 11.5%, P<0.05)." (PMID 28881613, 2017). "In one case of LGD, Smoc2 appeared to be limited to tumor bases, but Lgr5 and Ascl2 showed diffuse and patchy distribution." (PMID 28747693, 2017). "After successful LGR5 depletion, tumors shrank significantly but eventually regrew in parallel with LGR5 re‐expression, suggesting plasticity of LGR5− tumor cells." (PMID 28559443, 2017). "We discovered that the LGR5+ tumor cell population expresses a gene program similar to that of normal ISCs." (PMID 28468934, 2017). "Up-regulated expression of LGR5 was significantly correlated with larger tumor diameter (>5cm, P=0.001), higher TNM stage (P=0.021), recurrence (P=0.023) and metastasis (P=0.030) in the malignancy." (PMID 28881613, 2017). "Selective ablation of LGR5+ CSCs in LGR5-iCaspase9 knock-in organoids initially leads to tumor regression, but followed by tumor regrowth driven by re-emergence of LGR5+ CSCs from other cells." (PMID 29064439, 2017). "The mechanisms of the functional roles of LGR5 in enhancing different aspects of tumor malignancy remain poorly defined." (PMID 28881613, 2017). "Lgr5 expressed in intestinal stem cells has also been shown to self-renew and continuously replenish tumor progeny." (PMID 28160571, 2017). "Among R-Spondins (RSPO) ligands family, RSPO2 binding to Lgr5 regulates receptor turnover through stabilization of tumor suppressors ZNFR3 and RNF43 membrane E3 ligases, that mediate ubiquitination and consequent degradation of LRP6/5 receptors." (PMID 29354056, 2017). "The frequency of tumor-initiating LGR5+ HeLa-LGR5 cells (1/46) was 136.4-fold higher than that of the LGR5– HeLa-AcGFP cells (1/6,276; P<0.001)." (PMID 28880275, 2017). "Our results showed that the expression of LGR5 was significantly higher in liver tumor tissues than in adjacent non-tumor tissues." (PMID 28881613, 2017). "Expression of ABCB5 and Lgr5 in the bone marrow was dependent on tumor grading (both p=0.01) and T-category (p=0.036 and p=0.031, respectively)." (PMID 34221246, 2017). "Our study comprehensively analyzed the contribution of Bmi1+ and Lgr5+ cells to tumor initiation and propagation using multi-color cell-fate mapping." (PMID 28176811, 2017). "A reduction in CD44 and LGR5 expression suggested that the drug had an effect on tumour cells with stem characteristics." (PMID 29167573, 2017).
tumor (continued). "Both LGR5+ and LGR5– SiHa cells administered at the dose of 104, 103 or 102 cells led to tumor formation." (PMID 28880275, 2017). "The positive correlation between LGR5+ cells and Wnt activation was also confirmed in localization analyses of LGR5+ cells, which were transformed into neoplasia following nuclear accumulation of β-catenin due to APC deletion." (PMID 28757546, 2017). "Quantification of clone number over time showed that the number of cells generated by LGR5+ cells was directly proportional to the expansion kinetics of the tumor epithelial compartment." (PMID 28468934, 2017). "Up-regulated expression of LGR5 was significantly correlated with larger tumor diameter (>5cm, P=0.001), higher TNM stage (P=0.021), recurrence (P=0.023) and metastasis (P=0.030) in HCC." (PMID 28881613, 2017). "The frequency of tumor-initiating LGR5+ SiHa-LGR5 cells was 1/36, which was 17.4-fold higher than that of the LGR5– SiHa-AcGFP cells (1/627; P<0.001)." (PMID 28880275, 2017). "Next, we examined the presence of Lgr5+ tumorigenic cells and their ability to clonally expand in three tumor models using a similar experimental approach." (PMID 28176811, 2017). "Remarkably, this adaptation is not merely due to in vitro growth conditions but was a characteristic already present in the original tumours, both presenting a high number of LGR5+ cells and high mitotic index." (PMID 28114961, 2017). "As a CSC marker, LGR5 has been shown to be progressively expressed in cervical carcinogenesis and to promote cancer cell proliferation and tumor formation." (PMID 28880275, 2017). "At tumor initiation and during tumor propagation in the colon, the descendants of Lgr5-positive cells clonally proliferated to form clusters." (PMID 28176811, 2017). "Differences in gene expression profiles of ABCB5, Lgr5, CD133, and CK20 dependent on the underlying tumor disease and thus on each T, and UICC stage was additionally compared between three different groups of patients." (PMID 34221246, 2017). "We also performed for first time experiments of lineage tracing in human CRC, which demonstrate that LGR5+ tumor cells produce progeny over long periods of time, which undergo differentiation to distinct lineages." (PMID 28468934, 2017). "In CRC, LGR5 expressing tumor cells are a subset of tumor cells and share properties inherent to the ISC such as self-renewal capacity." (PMID 29127379, 2017). "To compare the ability of Lgr5- or Bmi1-positive cells to clonally expand at tumor initiation and development, we examined mice injected with tamoxifen before tumorigenesis." (PMID 28176811, 2017). "A recent study has also shown that LGR5 regulates the tumor-initiating ability of CSCs and that selective apoptosis of LGR5+ cells decreases tumor formation in human organoids." (PMID 28757546, 2017). "Although the evidence remains controversial, our lineage tracing for Bmi1-positive and Lgr5-positive cells during tumor initiation and propagation supports the monoclonal theory." (PMID 28176811, 2017). "In contrast, the oncogenes MYC and MYB, the expression of which is driven by the WNT pathway in CRC, remained elevated in quiescent and proliferating LGR5+ tumor cell populations." (PMID 28468934, 2017). "In xenograft experiments, human LGR5+ tumor cells propagated the disease to recipient mice with high efficiency implying that this cell population is largely enriched in tumor‐initiating cells." (PMID 28468934, 2017). "Our main interest in this study was to investigate the role of Lgr5+ stem cells in tumor formation in the skin." (PMID 27409834, 2016). "In the normal skin comparator for these tumours, but also at earlier time points, the LGR5+ve cells and their progeny were localized in their normal compartment." (PMID 27558455, 2016). "It has been proposed that stem cell quiescence acts as a tumour suppresive mechanism in murine skin, and that LGR5+ve stem cells are refractory to oncogenic transformation." (PMID 27558455, 2016).